TTC34 (tetratricopeptide repeat domain 34)
Tractability: No criterion of Open Targets' tractability assessment is met for any kind of drug.
Gene: Protein-coding gene on chromosome 1 (2,636,986 to 2,801,693, reverse strand). Ensembl gene ENSG00000215912.
Genetic constraint (gnomAD): Loss-of-function variants: 38 observed, 33.96 expected, observed/expected ratio (o/e) 1.12, 90% interval 0.86 to 1.47. The upper end of that interval is the gene's LOEUF score, 1.47, which puts it in group 6 of 6, group 1 being the genes least tolerant of losing a copy. Missense variants: 804 observed, 728.48 expected, observed/expected ratio (o/e) 1.1, 90% interval 1.04 to 1.17. Synonymous variants: 392 observed, 341.01 expected, observed/expected ratio (o/e) 1.15, 90% interval 1.06 to 1.25.
Homologues: Orthologues: chimpanzee TTC34 (82% identical), dog TTC34 (77% identical), pig TTC34 (76% identical), rat Ttc34 (72% identical), mouse Ttc34 (72% identical), macaque TTC34 (49% identical), tropical clawed frog ttc34 (42% identical), zebrafish ttc34 (20% identical). Paralogues in human: TTC6 (12% identical), CFAP70 (12% identical), OGT (11% identical), TTC7B (10% identical), TTC7A (9% identical), TMTC2 (9% identical), TMTC1 (8% identical), TTC16 (8% identical), TMTC3 (7% identical), IFT88 (7% identical), TMTC4 (7% identical), TTC13 (7% identical), and 2 more.
Diseases named in the same sentence as TTC34 in open-access papers:
TTC34 is named in the same sentence as 7 diseases in open-access papers, as found by Europe PMC text mining. Sharing a sentence is not in itself a finding about the gene and the disease. The quoted sentences say what the papers report.
systemic lupus erythematosus (2 papers, 2014 to 2024). An autoimmune multi-organ disease typically associated with vasculopathy and autoantibody production. "TTC34 gene a link with systemic lupus erythematosus was reported by some studies." (PMID 38373892, 2024).
amyotrophic lateral sclerosis (1 paper, 2021). Amyotrophic lateral sclerosis (ALS) is a neurodegenerative disease characterized by progressive muscular paralysis reflecting degeneration of motor neurons in the primary motor cortex, corticospinal tracts, brainstem and spinal cord. "Moreover, we identified Wald ratio effects between four genes (IQCB, TTC34, MPV17L2 and SLC30A7) and multiple sclerosis risk, and effects between two genes (SCFD1, G2E3) and amyotrophic lateral sclerosis risk." (PMID 33417599, 2021).
autoimmune disease (1 paper, 2024). A disorder resulting from loss of function or tissue destruction of an organ or multiple organs, arising from humoral or cellular immune responses of the individual to their own tissue constituents. "Among them, SH2B3, CLEC16A, and TTC34 are mainly involved in immune regulation and autoimmune diseases, while other genes are involved in regulating neurological, adrenal gland, and skeletal muscle-related diseases." (PMID 38943194, 2024).
breast carcinoma (1 paper, 2021). "Breast cancer patients with higher expression level of TTC34, CNTRL, TMEM151B, hsa-miR-5691, and hsa-miR-92a-1-5p showed the higher OS." (PMID 34055638, 2021). "The results suggested that metastasis associated RNAs, including AHRR, TTC34, CNTRL, ANKRD52, BCAR1, TMEM151B, PANX2, hsa-miR-105-5p, hsa-miR-4435, hsa-miR-5691, hsa-miR-92a-1-5p, and LINC01742 could serve as the prognostic biomarkers of breast cancer patients." (PMID 34055638, 2021).
rheumatoid arthritis (1 paper, 2018). A chronic, systemic autoimmune disorder characterized by inflammation in the synovial membranes and articular surfaces. "In our study, there were six novel loci outside of this region where genetic variation may influence rheumatoid arthritis risk via changes in DNA methylation (TTC34, MMEL1, AFF3, IRF5, CXCR5 and PGAP3)." (PMID 29893838, 2018).
TTC34 also shares sentences with these, for which no sentence is quoted: malignant neoplasms (1 paper); multiple sclerosis (1).